ACIN1 (apoptotic chromatin condensation inducer 1)
Description:
Auxiliary component of the splicing-dependent multiprotein exon junction complex (EJC) deposited at splice junction on mRNAs. The EJC is a dynamic structure consisting of core proteins and several peripheral nuclear and cytoplasmic associated factors that join the complex only transiently either during EJC assembly or during subsequent mRNA metabolism. Component of the ASAP complexes which bind RNA in a sequence-independent manner and are proposed to be recruited to the EJC prior to or during the splicing process and to regulate specific excision of introns in specific transcription subsets; ACIN1 confers RNA-binding to the complex. The ASAP complex can inhibit RNA processing during in vitro splicing reactions. The ASAP complex promotes apoptosis and is disassembled after induction of apoptosis. Involved in the splicing modulation of BCL2L1/Bcl-X (and probably other apoptotic genes); specifically inhibits formation of proapoptotic isoforms such as Bcl-X(S); the activity is different from the established EJC assembly and function. Induces apoptotic chromatin condensation after activation by CASP3. Regulates cyclin A1, but not cyclin A2, expression in leukemia cells.
Synonyms: Acinus; KIAA0670; fSAP152; ACN
Tractability: Antibody: its Gene Ontology location is reachable by antibodies, with high confidence. PROTAC: UniProt records ubiquitination sites on it; ubiquitination databases record sites on it; its protein half-life has been measured.
Gene: Protein-coding gene on chromosome 14 (23,058,561 to 23,095,614, reverse strand). Ensembl gene ENSG00000100813.
Subcellular location: Nucleus; Nucleus speckle; Nucleus, nucleoplasm
Subcellular location (Human Protein Atlas): Nucleoplasm; Cytosol
Pathways (Reactome):
Metabolism of RNA: mRNA Splicing - Major Pathway
Programmed Cell Death: Apoptotic cleavage of cellular proteins
Gene Ontology:
Molecular function: protein binding; RNA binding; ATP hydrolysis activity; enzyme binding; nucleic acid binding
Biological process: apoptotic chromosome condensation; erythrocyte differentiation; positive regulation of apoptotic process; positive regulation of monocyte differentiation; regulation of mRNA processing; RNA splicing
Cellular component: ASAP complex; nuclear speck; nucleoplasm; nucleus; cytosol; nuclear lumen
Genetic constraint (gnomAD): Loss-of-function variants: 14 observed, 146.39 expected, observed/expected ratio (o/e) 0.0956, 90% interval 0.062 to 0.15. The upper end of that interval is the gene's LOEUF score, 0.15, which puts it in group 1 of 6, group 1 being the genes least tolerant of losing a copy. Missense variants: 1,324 observed, 1,631.7 expected, observed/expected ratio (o/e) 0.81, 90% interval 0.77 to 0.85. Synonymous variants: 552 observed, 595.64 expected, observed/expected ratio (o/e) 0.93, 90% interval 0.86 to 0.99.
Homologues: Orthologues: chimpanzee ACIN1 (99% identical), macaque ACIN1 (98% identical), dog ACIN1 (92% identical), rabbit ACIN1 (92% identical), guinea pig ACIN1 (90% identical), rat Acin1 (87% identical), mouse Acin1 (86% identical), tropical clawed frog acin1 (53% identical), zebrafish acin1b (38% identical), zebrafish acin1a (25% identical), Drosophila melanogaster Acn (16% identical), Caenorhabditis elegans acin-1 (14% identical).
Diseases named in the same sentence as ACIN1 in open-access papers:
ACIN1 is named in the same sentence as 24 diseases in open-access papers, as found by Europe PMC text mining. Sharing a sentence is not in itself a finding about the gene and the disease. The quoted sentences say what the papers report.
lung carcinoma (5 papers, 2018 to 2025). "Emerging evidence indicates that ACIN1 is abundantly expressed in lung cancer patients compared to that in healthy individuals and that a high methylation level of ACIN1 predicts a high risk of lung cancer." (PMID 35255776, 2022). "In 2018, Xue et al8 found that the expression level of Acin1 mRNA in platelets of lung cancer patients was significantly higher than that of healthy control group, and the change in its level had potential clinical value for the diagnosis of lung cancer." (PMID 39128105, 2024). "This study analyzed the expression of ACIN1 mRNA in platelets, and explored its potential as a biomarker of lung cancer." (PMID 30201066, 2018). "The expression level of ACIN1 mRNA in platelets of patients with lung cancer was significantly higher than that in platelets of healthy controls (P=0.015)." (PMID 30201066, 2018). "The ROC curve showed that the area under the curve of ACIN1 mRNA for detecting lung cancer were 0.608." (PMID 30201066, 2018). "ACIN1 mRNA was highly expressed in platelets of lung cancer patients, and the detection of its expression level might have potential clinical value for the diagnosis of lung cancer." (PMID 30201066, 2018).
colorectal cancer (2 papers, 2022 to 2024). A primary or metastatic malignant neoplasm that affects the colon or rectum. "While previous studies have shown that ACIN1 may activate proapoptotic signaling pathways in colorectal cancer, we hypothesize that it may work synergistically together with ESR2, a known tumor suppressor in CRC." (PMID 39201394, 2024).
COVID-19 (2 papers, 2022 to 2023). A disease caused by infection with severe acute respiratory syndrome coronavirus 2. "However, these apoptotic gene signatures were characterized by distinct DEGs expressed in the COVID-19(+) TV (BCLAF1, BCL2L1) and COVID-19(-) PU control groups (BAD, ACIN1, HIF1A)." (PMID 37026002, 2023).
lung adenocarcinoma (2 papers, 2012 to 2021). A carcinoma that arises from the lung and is characterized by the presence of malignant glandular epithelial cells. "Hypermethylation of the ACIN1 was also found in non-tumorous regions of early stage lung adenocarcinoma cases and this could be one of the early events in cancer development." (PMID 22629410, 2012).
Intestinal tumors (1 paper, 2022). "Moreover, the ACIN1 (an apoptosis-related gene) regulon was associated with a better prognosis (OS HR 0.73 and DSS HR 0.68 and PFI HR 0.67) and with high activity in Intestinal tumors (p-value < 0.001)." (PMID 36230884, 2022).
osteosarcoma (1 paper, 2023). A usually aggressive malignant bone-forming mesenchymal neoplasm, predominantly affecting adolescents and young adults. "Of note, 0.28% of all splicing events, such as ES in NDEL1 and ACIN1, exhibited osteosarcoma specificity but also patient heterogeneity." (PMID 37457661, 2023).
pancreatic cancer (1 paper, 2012). "TNFRSF10C SN1 methylation in peripheral blood was well correlated with the methylation levels of LINE-1, Alu, p16, ACIN1 and RARbeta in pancreatic cancer tissue." (PMID 22629410, 2012). "In the first category, we could find only one instance of ‘self’ correlating loci as methylation of ACIN1 SN1 exhibited a strong positive correlation between pancreatic cancer tissues and peripheral blood (r = 0.788, p<0.001)." (PMID 22629410, 2012).
pancreatic tumor (1 paper, 2012). "However, TNFRSF10C methylation in the blood of cancer patients positively correlated with LINE-1, Alu and ACIN1 and negatively with p16 and RARbeta in pancreatic tumor tissue." (PMID 22629410, 2012). "In the second category, we could distinguish two such correlations; first ACIN1 SN1 in blood correlated with p16 SN2 in pancreatic tumor tissue (ρ = −0.528, p = 0.006) and, reciprocally, p16 SN2 in blood correlated with ACIN1 SN1 in pancreatic tumor tissue (ρ = −0.519, p = 0.007)." (PMID 22629410, 2012). "We investigated methylation levels at selected CpG sites in the CpG rich regions at the promoter regions of p16, RARbeta, TNFRSF10C, APC, ACIN1, DAPK1, 3OST2, BCL2 and CD44 in the blood of 30 pancreatic tumor patients and in the blood of 49 matching controls." (PMID 22629410, 2012). "Moreover, RARbeta in blood correlated with TNFRSF10C, CD44, ACIN1, APC, p16 and LINE-1 in pancreatic tumor tissue." (PMID 22629410, 2012).
prostate carcinoma (1 paper, 2024). A carcinoma that arises from epithelial cells of the prostate gland. "Notably, ACIN1 expression has been linked to bicalutamide resistance, a first-generation drug used in androgen deprivation therapy for prostate cancer." (PMID 39201394, 2024).
squamous cell carcinoma (1 paper, 2020). A carcinoma arising from squamous epithelial cells. "Subsequently, it was shown that S385 DNp63a phosphorylation is induced by cisplatin in squamous cell carcinoma cells, leading to RNA splicing and ACIN1-mediated cell death via interaction with spliceosome components SAP18, RBM38, ELAVL, SRPK2, SRSF2, and ACIN1." (PMID 33375680, 2020).
tumor (7 papers, 2012 to 2025). "Through whole transcriptome sequencing and RT-qPCR, we found that Acin1 was significantly upregulated in tumor tissues compared with normal control liver tissues and paracancerous tissues (P < .001)." (PMID 39128105, 2024). "The results of sequencing data showed that Acin1 was expressed in all sample tissues, and Acin1 mRNA was significantly upregulated in tumor tissues compared with paracancerous tissues and healthy control tissues (P < .001)." (PMID 39128105, 2024). "The weight and growth curve of xenograft tumors showed that the METTL3 knockdown led to a significant reduction in the weight and volume of tumor tissues, while Ad-ACIN1 also reversed the sh-METTL3 roles." (PMID 35255776, 2022). "The three most highly phosphorylated SRPK1-interacting proteins were the tumor-associated genes BCLAF1 and THRAP3, and apoptotic chromatin condensation inducer 1 (ACIN1), all three of which were found to interact with RNA Polymerase II." (PMID 35719374, 2022). "The results showed that Acin1 mRNA was also significantly upregulated in tumor tissue (P < .001)." (PMID 39128105, 2024). "We investigated the impact of METTL3 and ACIN1 on tumor growth in vivo." (PMID 35255776, 2022). "Additionally, high methylation levels at TNFRSCF10C were associated with positive perineural spread of tumor cells, while higher methylation levels of TNFRSF10C and ACIN1 were significantly associated with shorter survival." (PMID 22629410, 2012). "Research indicates that METTL3 facilitates tumor progression by regulating genes such as Bcl-2, EPPK1, and ACIN1." (PMID 40572597, 2025). "Finally, we investigated genes displaying similar expression patterns as ESR2 in tumor tissues, identifying potential co-expressed genes that may exert a synergistic effect on clinical outcomes, with significant results, including the expression of ACIN1, SYNE2, TNFRSF13C, and MDM4." (PMID 39201394, 2024).
cancer (4 papers, 2012 to 2024). A tumor composed of atypical neoplastic, often pleomorphic cells that invade other tissues. "Specific proteins in the KEGG pathway included ACIN1, serine/arginine-rich splicing factors, and Ubiquitin specific peptidase, the differential expression of which have been associated with altered cell proliferation and poor cancer prognosis, among others." (PMID 34068174, 2021). "ACIN1 and SYNE2 showed a combined effect with ESR2 on either OS or DFS in 9 out of 17 cancer types, TNFRSF13C showed a combined effect with ESR2 in 8 cancer types, and MDM4 showed a combined effect with ESR2 in 7 cancer types." (PMID 39201394, 2024). "Association between hypermethylation of CpGs of promoters of tumor suppressor genes and cancer specific survival was evident only at two CpGs, namely TNFRSF10C SN1 and ACIN1 SN1." (PMID 22629410, 2012).
ACIN1 also shares sentences with these, for which no sentence is quoted: acute lymphoblastic leukemia (2 papers); hepatocellular carcinoma (2); breast carcinoma (1); co-infection (1); cutaneous squamous cell carcinoma (1); depression (1); esophageal squamous cell carcinoma (1); head and neck cancer (1); infection (1); laryngeal squamous cell carcinoma (1); liver cancer (1); neuroblastoma (1).